CAV1 (caveolin 1)
Diseases named in the same sentence as CAV1 in open-access papers (continued):
Sharing a sentence is not in itself a finding about the gene and the disease.
tumor (continued). "Furthermore, Dcn, Cav1, Cdkn1a, Myc, Qsox1, and Pdgfr-b are known for their role in promoting tumor-cell aggressiveness, EMT and sustaining the proliferation of mesenchymal cells." (PMID 34775465, 2021). "Overall, the Cav-1 expression levels in the tumor microenvironment are quantifiable via digital image analysis and could potentially serve as a diagnostic biomarker assay." (PMID 34813586, 2021). "The differences in the molecular structure of the two isoforms of Cav-1 could possibly explain the different roles that Cav-1 can play in tumor progression." (PMID 33774714, 2021). "With respect to GB molecular subtype classification, some 85 patients of the original 152 cohort were sub-typed, and within which we found Cav-1 tumour expression to be significantly greater in the mesenchymal and proneural GB subtypes (combined 60% of the population)." (PMID 34490102, 2021). "Besides, silencing CAV-1 in 786-O cells impaired the potential for tumor sphere formation and the levels of stemness markers." (PMID 33935779, 2021). "However, in the absence of E-cadherin, CAV1 still functions as a tumor suppressor, albeit less efficiently, indicating that additional mechanisms must be invoked to explain CAV1 function as a tumor suppressor." (PMID 32825247, 2020). "Also, such studies open up the possibility of developing therapeutic strategies to prevent tumor progression and metastasis by downregulating CAV1 and thereby reducing the transport of pro-metastatic cargoes to nearby and distant recipient cancer cells." (PMID 32458269, 2020). "Also, CAV1 stabilizes cell–cell contacts and inhibits the spread of tumor cells during metastasis by favoring the plasma membrane localization of E-cadherin and p120-Catenin and the development of adherent junctions in ovarian carcinoma cell lines." (PMID 32458269, 2020). "Therefore, it is likely that CAV1 exerts its tumor suppressor activity by altering the activation kinetics of UPR sensors like PERK in the ER." (PMID 32811828, 2020). "Moreover, S80A mutation led to loss of the ability of CAV1 to inhibit the UPR, suggesting that S80 is important for the ability of CAV1 to suppress tumor growth." (PMID 32811828, 2020). "Therefore, CAV1 function as a tumor suppressor appears attributable, at least in part, to its ability to counteract the function of tumor-promoting proteins like AMF." (PMID 32458269, 2020). "Hence, our data suggest that celastrol promote its own transport to tumor tissues by disrupting microvascular structures and promoting the caveolin-1-related transcellular pathway." (PMID 32116702, 2020). "Here, shRNA-mediated CAV1 knockdown enhanced tumor growth compared to B16F0(shLuc) control cells." (PMID 32825247, 2020). "We found that overexpression of Cav-1 could significantly improve the tumor cell survivals after cisplatin treatment, while GC cells were more sensitive to cisplatin in the absence of Cav-1." (PMID 32117718, 2020). "Hence, the results indicated that the expression of miR-203 and CAV1 was closely related to the clinical stage, and tumor differentiation degree." (PMID 32990143, 2020). "CAV1 shows a tumor-dependent and tissue-dependent role of tumors." (PMID 32401768, 2020). "Moreover, CAV1 silencing increases the expression of E-cadherin, integrin β4, and desmoplakin, thereby favoring epithelial integrity and inhibiting the tumor spread." (PMID 32458269, 2020). "Additionally, the average metastatic tumor quantity in the liver was approximately 5 times less in mice treated with caveolin-1 siRNA-expressing SMMC7721 cells compared to mice treated with negative control SMMC7721 cells." (PMID 32676485, 2020). "In summary, CAV1-dependent tumor suppression in the absence of E-cadherin is linked to reduced HIF1α transcriptional activity via diminished NOS-mediated HIF1α S-nitrosylation." (PMID 32825247, 2020). "In oral cancer, an increase in CAV1 expression represents a marker of tumor progression." (PMID 32759810, 2020).
tumor (continued). "Caveolin-1 (CAV1), a member of the caveolin family of proteins, is a scaffolding protein with a controversial role in cancer, given that it has been ascribed roles both as a tumor suppressor and a promoter of metastasis." (PMID 32825247, 2020). "Of note, CAV1-expressing EC seemed to remain ceramide- and ASMase-positive upon tumor progression." (PMID 32273493, 2020). "In vivo, CAV1-mediated tumor suppression was dependent on NOS activity." (PMID 32825247, 2020). "Therefore, further studies are necessary to obtain a better understanding of the function of CAV1 in tumor progression." (PMID 32386516, 2020). "It has been reported, that in this context CAV1 acts as tumor suppressor." (PMID 32825330, 2020). "CAV1 is downregulated in human tumors, tumor cell lines and oncogene-transformed cells." (PMID 32811828, 2020). "Downregulated Cav‐1 expression of cancer‐associated fibroblasts is observed in many aggressive cancers, indicating that Cav‐1 may inhibit tumor cell growth and increase the production of α‐smooth muscle actin, responsible for poor cancer outcomes." (PMID 32508059, 2020). "Thus, while the mechanism by which E-cadherin and CAV1 synergize in tumor suppression is well defined, it remained unclear how E-cadherin blocks the ability of CAV1 to promote migration, invasion and metastasis." (PMID 32152405, 2020). "In addition to the increased unsaturated C24:1 ceramide species detected in the more radio-resistant CAV1(+) PC3 cells, CAV1-deficient fibroblasts, as found in advanced, more radio-resistant tumor stages, showed significantly upregulated C24:1 ceramide levels." (PMID 32273493, 2020). "Taken together, previous studies suggested that CAV1 expression may inhibit tumor growth in the early stages of cancer, and promote its invasion and metastasis in the later stages." (PMID 32243098, 2020). "In addition, plasma Cav-1 levels tended to be elevated in RM-9 tumor-bearing mice compared to control mice." (PMID 32855410, 2020). "Furthermore, increased glycolysis observed in stromal fibroblasts that nourish surrounding tumor cells show reduced CAV1 expression like fLfs." (PMID 32841217, 2020). "In addition, CAV1 reprograms the TGF-β signaling pathway from suppressing tumor formation to being oncogenic." (PMID 32458269, 2020). "Recent studies have shown that tumor cell-derived exosomes play a prominent role in the pathology of tumor metastases by using tumor-signaling pathway such as caveolin-1, HIF-1a, miR-21, miR-105, miR-210, β-catenin and oncogenic kinases (e.g., mutated EGFR, RAS and MAP kinases)." (PMID 32257377, 2020). "Particularly, this gene functions predominantly as a tumor suppressor as early as the onset of tumorigenesis, whereas a positive correlation was found between a higher Cav-1 expression with a more advanced level of tumor malignancy and also a worse clinical outcome." (PMID 33381039, 2020). "Interestingly, plasma levels of Cav-1 and identified lipid species that are part of our Cav-1 sphingolipid signature increased upon treatment with eliglustat in RM-9 tumor bearing mice." (PMID 32855410, 2020). "Here, we evaluate the mechanisms underlying tumor suppression by CAV1 in cancer cells lacking E-cadherin in hypoxia." (PMID 32825247, 2020). "Accordingly, it suggested that these 3 downregulated proteins (ANPEP, CAV1, and TGM2) were potentially remained downregulated and might associate with the loss of vascular structures in tumor metastases." (PMID 32756007, 2020). "In NSCLC tumor tissues and A549 cell line, Caveolin 1 (CAV1) was described to upregulate HOTAIR." (PMID 32438606, 2020). "Similar to Cav-1, Cav-2 involvement in tumorigenesis seems to depend on the tumor type." (PMID 33195223, 2020). "Moreover, downregulation of caveolin-1 and up-regulation of monocarboxylate transporter 4 was detected in CAFs and tumor cells, transferring lactate into neoplastic cells to growth ATP formation." (PMID 32781778, 2020).
tumor (continued). "The tumor inhibiting role of stromal CAV1 can be explained in this way." (PMID 32401768, 2020). "Interestingly, the tumor suppressor activity of CAV1 was abrogated by site-directed mutagenesis of S80, correlating with a reduced ability to repress the UPR." (PMID 32811828, 2020). "Some studies indicate that the normal and elevated expression of Cav-1 can significantly inhibit tumor cells proliferation, invasion, and metastasis, thus it can be concluded that the function loss and down-regulation of Cav-1 is a meaningful marker in cancer progression." (PMID 31759347, 2019). "In addition, Cav-1 modulates autophagy and the formation of invadopodia and target regulated by miRNAs to affect tumor progress." (PMID 31759347, 2019). "Moreover, studies have shown that the overexpression of CAV-1 is usually found in multidrug-resistant tumor cells and indicates poor prognosis in cancer patients." (PMID 30981205, 2019). "As part of the Reproducibility Project: Cancer Biology we published a Registered Report that described how we intended to replicate selected experiments from the paper ‘Biomechanical remodeling of the microenvironment by stromal caveolin-1 favors tumor invasion and metastasis’." (PMID 31845647, 2019). "Different types of tumor cells are correlated with Cav-1 in various ways." (PMID 31297035, 2019). "However, Cav-1 has been discovered to be up-regulated in the advanced tumor stage of different kinds of cancers, demonstrating its association with invasion and metastasis." (PMID 31759347, 2019). "Tumor-derived reactive oxygen species (ROS) are responsible for down-regulation of CAV1 in CAFs." (PMID 31067787, 2019). "Collectively, these observations strongly indicate that Cav1 may act as a tumor suppressor or oncogene depending on the cell type in which its function is dysregulated." (PMID 31534543, 2019). "For example, Cav-1 displays its role as a tumor-suppressor requiring the presence of E-cadherin." (PMID 31759347, 2019). "High levels of pCav1 as indicated by Cav1 Y14D MDA-MB-435 expression inhibited tumor growth." (PMID 31803361, 2019). "Recent researches indicate that CAV1 functions as a tumor suppressor in OC." (PMID 31228941, 2019). "CAV-1 levels are positively correlated with tumor stage/grade in a number of cancer types and regulates multiple cancer-associated processes including cellular transformation, tumor growth, cell migration, cell death and survival, multidrug resistance and angiogenesis." (PMID 31889941, 2019). "Clinically, data from two cohorts of PCa obtained from Oncomine database (Vanaja Prostate dataset [203065_s_at]28 and Lapointe Prostate dataset [290525]29) indicated that Cav-1 mRNA expression was significantly higher in metastasis specimens compared with the primary tumor specimens." (PMID 31685812, 2019). "The different roles of Cav-1 in cancer may depend on the stage of cancer and its interaction with multiple different signaling molecules in specific tissues and cell types, thus it remains controversial whether Cav-1 acts as an tumor-promoter or a suppressor." (PMID 31759347, 2019). "Furthermore, CAV1 plays important roles in tumorigenesis and shows to act as a tumor-promoter or suppresser depending on the tumor cell types and subtypes." (PMID 31228941, 2019). "Up-regulated expression of Cav-1 induced by the activation of tumor promoter 12-O-tetradecanoyl-phorbol-13-acetate (4β-TPA) is associated with enhanced malignancy behavior of endometrial cancer cells through increasing cells anchorage-independent growth, invasion, and migration." (PMID 31759347, 2019). "Expression of CAV1 in LNCaP cells increased cell proliferation and tumor growth in vivo." (PMID 31362353, 2019). "However, miR-203 positively regulates the expression of Cav-1 and plays a synergistic effect in inhibiting tumor invasion and migration in Panc-1 cells." (PMID 31759347, 2019).
tumor (continued). "Based on these and other findings, it may be proposed that perturbation of CA9 glycosylation and/or caveolin-1 provides improved opportunities for enhanced targeting of the acidic tumor niche." (PMID 30767150, 2019). "These dual roles for pCav1 may in part account for previously reported tumor suppressor and progression activities of Cav1." (PMID 31803361, 2019). "In cervical SCC, expression of Cav-1 in tumor cells possibly contributes to cancer progression through enhancing cell proliferation, but little connection was reported between stromal tissues and Cav-1 expression." (PMID 31759347, 2019). "In murine mammary glands, loss of Cav-1 can increase the expression of ECM and α-SMA protein and change ductal architecture, which may lead to tumor initiation." (PMID 31759347, 2019). "Tumor cell-derived reactive oxygen species (ROS) decrease the expression of CAV1 in CAFs." (PMID 31014370, 2019). "SNCG in PRAD was also described to be activated by Cav-1 in the tumor microenvironment." (PMID 31238876, 2019). "However, contradictory result shows that stromal Cav-1 has a potential to facilitate tumor invasion and metastasis by regulating Rho activity, p190 localization, and phosphorylation." (PMID 31759347, 2019). "(C) Immunohistochemical analysis of TRIAP1, PCNA and CAV1 in isolated PC3 xenograft tumours." (PMID 30871022, 2019). "Some studies have suggested that Cav-1 promotes tumor progression." (PMID 31759347, 2019). "Cav-1, the mostly documented one, has been reported to be down-regulated in different types of human tumor samples, suggesting negative correlation between its expression level and tumor formation and progression, so acting as an tumor suppressor." (PMID 31759347, 2019). "Thus, the levels of Cav1 in the normal cells surrounding tumour are critical for providing tumour‐suppressive signals to constrain tumour progression." (PMID 29502342, 2018). "However, higher tumor Cav-1 level was significantly related with longer PFS of nab-paclitaxel and gemcitabine (Log-rank p = 0.03)." (PMID 30348118, 2018). "However, our data suggests that the temporal modulation of CAV1 extends the half-life of HER2 at the tumor cell surface to enhance the tumor’s avidity for trastuzumab." (PMID 30510281, 2018). "Equipped with this information, we analyzed patient tumor samples using immunofluorescence to understand how CAV1 expression patterns may relate to the cellular localization of HER2." (PMID 30510281, 2018). "CAV1 expression in CAFs correlates with higher remodeling capacity and facilitates tumor invasion." (PMID 30404014, 2018). "Furthermore, the role of Caveolin 1 has been reported in multiple cancers towards both tumor progression and tumor suppression." (PMID 29568375, 2018). "Based on these facts, we suppose that tumor and stromal Cav-1 expression may be a predictor of nab-paclitaxel efficacy." (PMID 30348118, 2018). "We performed a single arm, phase II study to evaluate the efficacy and safety of weekly nab-paclitaxel and gemcitabine combination in patients with metastatic breast cancer (MBC) and explored role of tumor/stromal Caveolin-1 (Cav-1) as a predictive biomarker for the efficacy." (PMID 30348118, 2018). "Furthermore, both H&E staining and the TUNEL assay revealed that the synergistic use of paclitaxel and ADQ resulted in significant increases of apoptosis in tumor tissues, accompanied by the decreased expression of Ki67 and CAV1." (PMID 30333750, 2018). "Recent in vitro research has shown that MDA-MB-231 and HeLa cells undergo a generalised reduction in overall internalisation of the tumor cell surface proteome in response to hypoxia, with a parallel selective upregulation of specific endocytic pathways, mediated via caveolin 1 (ref.63)." (PMID 30120388, 2018). "Tumor/stromal Cav-1 level may be a good predictor for the efficacy of nab-paclitaxel and gemcitabine." (PMID 30348118, 2018).
tumor (continued). "Additionally, we found that NIH3T3/635 cells showed a downregulated caveolin-1 mRNA level in the presence of tumor cells compared with those in mono-culture." (PMID 29435153, 2018). "This identifies another route that miR-376 may serve as a tumor suppressor, as it would be able to directly target and suppress CAV1, IGF1R, or both, to disrupt their oncogenic mission." (PMID 30042829, 2018). "(C) For patients stratified by tumor and stromal Cav-1 staining." (PMID 30348118, 2018). "This kind of cell-specific context-dependency is also reflected in the present study, where we show that CAV1 expression has strong inverse correlation with E-cadherin in KRT5-negative tumour cells, but weak positive correlation in KRT5-positive prostatic glands, which are mostly benign." (PMID 29402961, 2018). "Paracrine caveolin-1 can promote the release of various growth factors by regulating their transcription, upregulating their mRNA and protein expression levels, stimulating tumor angiogenesis, and promoting tumor formation and proliferation." (PMID 30424755, 2018). "It has been shown that CAV1 may possess both tumor suppressing and oncogenic functions, depending on progress and tumor type." (PMID 29850392, 2018). "It is interesting to note that positive regulation of cav-1 by NO is found in tumor cells." (PMID 30572925, 2018). "In sum, accumulating evidence has indicated that Cav-1 might act as a tumor suppressor in multiple malignant tumors." (PMID 28546853, 2017). "First, EGFR overexpressing tumour cells, high levels of STAT3 activity, loss of caveolin-1, Akt- and Myc- driven tumour cells, and argininosuccinate synthetase enzyme deficiency are all associated with a high autophagy dependency and are therefore more sensitive to CQ administration." (PMID 29225688, 2017). "Herein the role of Cav1 for the outcome of RT in the context of tumor-stroma interactions is still largely unknown." (PMID 28112237, 2017). "Cav-1 has been found to be highly expressed in mesenchymal cells including adipocytes, endothelial cells and smooth muscle cells and has been reported to act as a tumor suppressor." (PMID 28187162, 2017). "In addition, Cav1 has been characterized in some cell populations of the tumor stroma, where it also shows contrasting effects." (PMID 29212030, 2017). "There may be other reasons for these findings because two other groups injected tumor cells subcutaneously in Cav-1- and Cav-2−/− mice getting results similar to those from the Capozza study." (PMID 29250058, 2017). "As determined by tumor volume and weight, tumor growth was retarded by Cav‐1 knockdown." (PMID 28514055, 2017). "Sessa’s group injected Lewis lung carcinoma cells in wild-type and Cav-1−/− mice subcutaneously and found that angiogenesis, permeability, and tumor growth were enhanced, effects attributed to an increased phosphorylation of VEGFR and reduced association with VE-cadherin." (PMID 29250058, 2017). "Treatment of mice with cordycepin significantly suppressed tumor growth and upregulated CAV1 and JNK phosphorylation, whereas it inhibited the phosphorylation of Foxo3a and only slightly increased the total Foxo3a protein level as compared to untreated control." (PMID 28099944, 2017). "Besides, EMMPRIN can interact with a verity of proteins, such as VEGF, lewis y antigen, caveolin-1, cyclooxygenase-2 and fascin, executing its effect on tumorigenesis by regulating tumor cell invasion, metastasis and adhesion.." (PMID 29137291, 2017). "Moreover, pre-clinical investigations have demonstrated that epithelial cancer cells can induce the down-regulation of CAV1 in adjacent fibroblasts, leading to a specific, tumor-supportive, CAF phenotype." (PMID 28067804, 2017). "These Cav1-immunoreactive PC3 cells were again localized within fibroblast-enriched tumor regions." (PMID 28112237, 2017). "The role of Cav-1 protein in tumorigenesis and tumor progression still remains controversial." (PMID 28828003, 2017).